SIGLEC10 (sialic acid binding Ig like lectin 10)
Description:
Putative adhesion molecule that mediates sialic-acid dependent binding to cells. Preferentially binds to alpha-2,3- or alpha-2,6-linked sialic acid (By similarity). The sialic acid recognition site may be masked by cis interactions with sialic acids on the same cell surface. In the immune response, seems to act as an inhibitory receptor upon ligand induced tyrosine phosphorylation by recruiting cytoplasmic phosphatase(s) via their SH2 domain(s) that block signal transduction through dephosphorylation of signaling molecules. Involved in negative regulation of B-cell antigen receptor signaling. The inhibition of B cell activation is dependent on PTPN6/SHP-1 (By similarity). In association with CD24 may be involved in the selective suppression of the immune response to danger-associated molecular patterns (DAMPs) such as HMGB1, HSP70 and HSP90 (By similarity). In association with CD24 may regulate the immune repsonse of natural killer (NK) cells. Plays a role in the control of autoimmunity (By similarity). During initiation of adaptive immune responses by CD8-alpha(+) dendritic cells inhibits cross-presentation by impairing the formation of MHC class I-peptide complexes. The function seems to implicate recruitment of PTPN6/SHP-1, which dephosphorylates NCF1 of the NADPH oxidase complex consequently promoting phagosomal acidification (By similarity).
Synonyms: Siglec-10; SLG2; PRO940; MGC126774
Tractability: Antibody: its Gene Ontology location is reachable by antibodies, with high confidence; UniProt places it where antibodies can reach, with medium confidence; UniProt predicts a signal peptide or a membrane-spanning region; the Human Protein Atlas places it where antibodies can reach. Other modalities: a drug acting on it is in phase 2 or 3 trials.
Target class: Adhesion
Gene: Protein-coding gene on chromosome 19 (51,410,020 to 51,417,803, reverse strand). Ensembl gene ENSG00000142512.
Subcellular location: Cell membrane (Isoform 1); Cell membrane (Isoform 2); Cell membrane (Isoform 3); Cell membrane (Isoform 4); Secreted (Isoform 5)
Subcellular location (Human Protein Atlas): Cytosol; Actin filaments; Plasma membrane
Pathways (Reactome):
Immune System: Immunoregulatory interactions between a Lymphoid and a non-Lymphoid cell
Gene Ontology:
Molecular function: phosphatase binding; protein binding; SH2 domain binding; sialic acid binding
Biological process: negative regulation of inflammatory response to wounding; cell adhesion
Cellular component: actin cytoskeleton; cytosol; plasma membrane; extracellular region
Genetic constraint (gnomAD): Loss-of-function variants: 45 observed, 70.3 expected, observed/expected ratio (o/e) 0.64, 90% interval 0.5 to 0.82. The upper end of that interval is the gene's LOEUF score, 0.82, which puts it in group 3 of 6, group 1 being the genes least tolerant of losing a copy. Missense variants: 789 observed, 912.95 expected, observed/expected ratio (o/e) 0.86, 90% interval 0.81 to 0.92. Synonymous variants: 379 observed, 384.09 expected, observed/expected ratio (o/e) 0.99, 90% interval 0.91 to 1.07.
Homologues: Orthologues: chimpanzee SIGLEC10 (98% identical), macaque SIGLEC10 (90% identical), rat Siglec10 (60% identical), guinea pig Siglec10 (59% identical), mouse Siglecg (59% identical), tropical clawed frog siglecl2 (21% identical), tropical clawed frog siglecl1 (19% identical), tropical clawed frog siglecl2 (19% identical), tropical clawed frog siglecl1 (12% identical). Paralogues in human: SIGLEC11 (69% identical), SIGLEC5 (38% identical), SIGLEC8 (30% identical), SIGLEC12 (28% identical), SIGLEC9 (28% identical), SIGLEC7 (28% identical), SIGLEC14 (27% identical), SIGLEC6 (27% identical), CD33 (22% identical), SIGLEC1 (20% identical), SIGLEC16 (17% identical), MAG (16% identical), and 4 more.
Diseases named in the same sentence as SIGLEC10 in open-access papers:
SIGLEC10 is named in the same sentence as 34 diseases in open-access papers, as found by Europe PMC text mining. Sharing a sentence is not in itself a finding about the gene and the disease. The quoted sentences say what the papers report.
ovarian carcinoma (7 papers, 2020 to 2024). A malignant neoplasm originating from the surface ovarian epithelium. "It has been reported that CD24 is highly expressed and interacts with the inhibitory receptor sialic acid‐binding Ig‐like lectin 10 (Siglec‐10), which is expressed by tumor‐associated macrophages to promote immune evasion in ovarian cancer and breast cancer." (PMID 32394616, 2020). "Recent studies have found that CD24 on ovarian cancer (OC) and triple-negative breast cancer cells interacts with the inhibitory receptor sialic-acid-binding Ig-like lectin 10 (Siglec-10) on tumour-associated macrophages (TAMs) to inhibit phagocytosis by macrophages." (PMID 38702326, 2024). "Experimental targeting of SIGLEC10 with mAb against SIGLEC10 restored the phagocytosis properties of macrophages in preclinical models of ovarian cancer." (PMID 38033495, 2023). "Recently, CD24 was reported as a new ‘don't eat me signal’ which avoids phagocytosis by Siglec10‐expressing macrophages in breast and ovarian cancer, resulting in tumor cell survival." (PMID 35289116, 2022). "Siglec10 plays an important role in hepatocellular cancer, ovarian cancer, and triple-negative cancer." (PMID 36468012, 2022). "Ovarian cancer cells expressed CD24 could achieve the immune evasion through interacting with the receptor called sialic-acid-binding Ig-like lectin 10 (Siglec-10 has been reported to interact with the highly sialylated form of CD24), which is expressed by tumor associated macrophages (TAM)." (PMID 37359556, 2023).
breast carcinoma (5 papers, 2020 to 2023). "CD24 was specifically overexpressed in the tumor compartment, orchestrates a novel innate immune checkpoint through interaction with the inhibitory receptor sialic acid-binding Ig-like lectin 10 (Siglec-10) on tumor-associated macrophages in primary ovarian and breast cancer samples." (PMID 34215720, 2021). "Additionally, breast cancer cells overexpress CD24, while TAMs express high levels of Siglec‐10." (PMID 34914196, 2022).
hepatocellular carcinoma (5 papers, 2022 to 2024). A malignant tumor that arises from hepatocytes. "In patients with hepatocellular carcinoma, the up-regulation of SIGLEC10 has been associated with poor survival." (PMID 38338696, 2024). "A past study reported the association of SIGLEC10 in impeding NK cell function and poor patient survival in hepatocellular carcinoma (HCC); CD24/SIGLEC10 interaction may thus be involved in regulating NK cell function." (PMID 36371461, 2022). "Namely, TMEM163 implied in NK cell degranulation was down-regulated whereas SIGLEC10, which is thought to decrease NK cell cytotoxicity in hepatocellular carcinoma, was up-regulated." (PMID 39867888, 2024). "Furthermore, the study has shown that the interaction of CD24 and Siglec10 can produce immunosuppressive signals, resulting in natural killer cells (NK) dysfunction, allowing hepatocellular carcinoma (HCC) cells to avoid NK cytotoxicity of tumor cells." (PMID 37484024, 2023).
glioma (4 papers, 2021 to 2025). A benign or malignant brain and spinal cord tumor that arises from glial cells (astrocytes, oligodendrocytes, ependymal cells). "SIGLEC10 play a significant role in the regulation of inflammation in glioma through its close association with mediators, cells, and pathways involved in this process." (PMID 40548122, 2025). "For example, studies have shown that expression of FCGR2B and SIGLEC10 in gliomas was higher than in normal tissue where it was associated with a poor prognosis." (PMID 40894037, 2025). "In the TME, SIGLEC10 can act in conjunction with some immune checkpoints to promote the progression and metastasis of glioma by affecting the immune response." (PMID 40548122, 2025). "Siglec10 expression was higher in high-grade gliomas (grades 3 and 4) than low-grade gliomas (grade 2)." (PMID 36468012, 2022). "Siglec10 was correlated with inflammatory mediators, inflammatory cells, and inflammatory pathways in gliomas." (PMID 36468012, 2022). "Siglec10 was also correlated with immune checkpoints in gliomas." (PMID 36468012, 2022). "Siglec10 might take part in the immune response in the tumor microenvironment to induce glioma’s progression and metastasis." (PMID 36468012, 2022). "It has been reported that CD40, TNFSF14, LGALS9, and SIGLEC10 high expression levels are associated with glioma malignancy grade and negative prognosis." (PMID 35187044, 2021). "Siglec10 might correlate with other malignant factors in gliomas." (PMID 36468012, 2022).
cholangiocarcinoma (2 papers, 2020 to 2021). A carcinoma that arises from the intrahepatic biliary tree (intrahepatic cholangiocarcinoma) or from the junction, or adjacent to the junction, of the right and left hepatic ducts (hilar cholangiocarcinoma). "Of notice, while most SIGLEC family genes rarely mutated in cholangiocarcinoma and undifferentiated stomach adenocarcinoma, SIGLEC10 and SIGLEC7 were respectively highly mutated in each of them." (PMID 33240817, 2020).
colorectal cancer (2 papers, 2022 to 2024). A primary or metastatic malignant neoplasm that affects the colon or rectum. "We then examined the expression of Siglec‐10 on tumor‐infiltrating lymphocytes in human colorectal cancer (CRC)." (PMID 39373395, 2024).
COVID-19 (2 papers, 2022 to 2024). A disease caused by infection with severe acute respiratory syndrome coronavirus 2. "SIGLEC6 belongs to the family of sialic acid-binding immunoglobulin-like lectin proteins, out of which SIGLEC1, SIGLEC7 and SIGLEC10 have been implicated to play a role in COVID-19." (PMID 35438176, 2022).
bovine tuberculosis (1 paper, 2024). "Other genes found in the present study related to immunity and adaptation in literature were DNAJC17 (heat tolerance in Zebu cattle), GCHFR, MDGA2 (heat stress in cows), FOXF1, NKG7 (bovine tuberculosis response), and SIGLEC10." (PMID 39766784, 2024).
glomerulonephritis (1 paper, 2021). A renal disorder characterized by damage in the glomeruli. "Furthermore, an autoimmune phenotype involving high levels of autoantibody and mild glomerulonephritis was found in ageing C57BL/6 mice with Siglec‐10 deficiency." (PMID 33728669, 2021).
melanoma (1 paper, 2025). A malignant, usually aggressive tumor composed of atypical, neoplastic melanocytes. "Increased SIGLEC10 gene expression within the B cell population in human melanomas correlates with poor response to anti-PD1 therapy." (PMID 40894037, 2025). "Interestingly, we also observed a correlation between anti-PD1 therapy resistance and progression of disease in human melanoma patients that exhibited increased expression of SIGLEC10." (PMID 40894037, 2025). "Hypothesizing that similar mechanisms in a tumor microenvironment may attenuate anti-tumor immunity, we observed that expression of SIGLEC10, the human homolog of Siglecg, was associated with resistance to anti-PD1 therapy in human melanomas." (PMID 40894037, 2025). "First, we investigated whether SIGLEC10 and FCGR2B are highly expressed within the B cell population in human melanomas." (PMID 40894037, 2025).
Sepsis (1 paper, 2025). Sepsis is defined as life-threatening organ dysfunction caused by a dysregulated host response to infection. "CD24 was originally identified as involved in a series of inflammatory responses through binding with Siglec‐10 on innate immune cells, including in infection, sepsis, and liver damage." (PMID 41354057, 2025).
tauopathy (1 paper, 2022). Neurodegenerative disorders involving deposition of abnormal tau protein isoforms (tau proteins) in neurons and glial cells in the brain. "Siglecs, in particular Siglec10, are AD-enriched, as the level of Siglec-10 + cells in non-AD tauopathy was similar to that of control and low Braak stage AD, indicating that Siglec-10 could potentially serve as an AD biomarker and a potential therapeutic target associated with late-stage AD." (PMID 36536457, 2022).
thyroid cancer (1 paper, 2024). "The role of SIGLEC10 and SIGLEC11 genes in thyroid cancer is not yet investigated." (PMID 38338696, 2024).
tumor (57 papers, 2013 to 2026). "Tumor-expressed CD24 promoted immune evasion by interacting with the inhibitory receptor sialic-acid-binding Ig-like lectin 10 (Siglec-10), which is expressed by M2-like tumor-associated macrophages (TAMs)." (PMID 40770672, 2025). "Tumor Immune Estimation Resource (TIMER) analysis also indicated a positive association between Siglec‐10 expression and both CD8 and PD‐1 in human cancers." (PMID 39373395, 2024). "In other cancer types, SIGLEC10 is considered a pro-tumor marker and is associated with clinical aggressiveness." (PMID 38338696, 2024). "CD24 serves as another “don't eat me” signal, interacting with the inhibitory receptor Siglec‐10 on tumor‐associated macrophages." (PMID 39297408, 2024). "CD24, recently identified as highly expressed on tumor cells, interacts with sialic acid binding immunoglobulin-like lectin 10 (Siglec10) on tumor-associated macrophages, thereby evading efferocytosis." (PMID 39660125, 2024). "CD24 is abnormally overexpressed in many tumors compared to normal tissues, and Siglec10 expression is also higher in tumor-associated macrophages." (PMID 37484024, 2023). "The authors demonstrate that tumor-expressed CD24 promotes immune evasion by interacting with the inhibitory receptor sialic acid-binding Ig-like lectin 10 (siglec-10) expressed by tumor-associated macrophages." (PMID 36297672, 2022). "In another study, the possibility of CD24/SIGLEC10 interaction in TNBC under the exposure of tumor-associated macrophages (TAMs) was reported." (PMID 36371461, 2022). "have recently identified CD24, a glycosylphosphatidylinositol (GPI)-anchored protein, as a novel ‘don’t eat me’ signal expressed on tumor cells to evade macrophage-mediated phagocytosis by binding to Siglec10 inhibitory receptor expressed on tumour-associated macrophages." (PMID 39996058, 2025). "The macrophage‐expressed inhibitory receptor Siglec‐10 engages with tumor‐associated CD24 through interactions at its extracellular domain, which triggers intracellular signaling via immunoreceptor tyrosine‐based inhibitory motifs (ITIMs) located within its cytoplasmic tail." (PMID 40529613, 2025). "In addition, we found that ST6GALNAC3 was positively correlated with the immune checkpoints (SIRPA, LILRB1, SIGLEC10) of tumor associated macrophages involved in tumor antigen recognition disorders." (PMID 37138287, 2023). "These genes were highly enriched for immune response and adhesion by GO terms, including genes such as IFI27 (encoding Interferon alpha inducible protein 27, which can act also as a tumor suppressor) and SIGLEC10 (encoding sialic acid-binding Ig-like lectin 10)." (PMID 37024521, 2023). "Additionally, the SIGLEC10 expressed by tumor-associated macrophages can interact with CD24 to promote immune evasion." (PMID 33796453, 2021). "OAd-SIRPα-Fc and OAd-Siglec10-Fc have been shown to significantly suppress tumor growth in macrophage-rich tumor microenvironments, while OAd-TIGIT-Fc primarily enhances T cell activation." (PMID 40698086, 2025). "More recently, we showed that CRC‐derived CAFs express Siglec‐10 ligands that impact NK cell anti‐tumour function, which we propose is likely through engagement with Siglec‐10/G." (PMID 40667828, 2025). "Examination of tumor-infiltrating immune cells revealed that SIGLEC10 and FCGR2B are frequently and highly expressed within the B cell cluster." (PMID 40894037, 2025). "Blocking CD24 or Siglec‐10 expression by gene or antibody facilitates macrophage phagocytosis and inhibits tumor growth." (PMID 40529613, 2025). "Targeting Siglec‐10+ macrophages in GC through Siglec‐10 blocking enhanced anti‐tumour immunity and synergistically improved response to anti‐PD‐1 immunotherapy in ex vivo tumour models." (PMID 40667828, 2025). "Recent studies have indicated that surface CD24 in tumours is a novel antiphagocytic protein that interacts with sialic-acid-binding Ig-like lectin 10 (Siglec10) on macrophages." (PMID 38702326, 2024).
tumor (continued). "OAd-SIRPα-Fc treatment conferred better antitumor activity than OAd-Siglec10-Fc and OAd-TIGIT-Fc in the MC38 model, but OAd-Siglec10-Fc showed satisfactory tumor suppression in the 4T1 model." (PMID 38016957, 2023). "The interaction between CD24 on cancer cells and Siglec‐10 on macrophages inhibits the phagocytosis of tumor cells by macrophages." (PMID 36866919, 2023). "The results elucidated a crucial role of CD24 in tumor immunosuppression via interaction with Siglec‐10, which acts as a “don't eat me” signal." (PMID 36866919, 2023). "Through overexpression of CD24, tumor cells interact with Siglec10, which inhibits the activity of macrophages and achieves immune escape." (PMID 37484024, 2023). "2.The interaction between the immune checkpoint proteins CD24 and LGALS9 in tumor epithelial cells, SIGLEC10 in dendritic cells, SIGLEC10 and HAVCR2 in macrophages increased." (PMID 37671151, 2023). "Increased expression of Siglec10, SIRPα, and TIGIT was significantly associated with the infiltration levels of neutrophils and dendritic cells (DCs) in almost all tumor types except THYM." (PMID 38016957, 2023). "To characterize the precise effects of OAds, we evaluated antitumor activity in three tumor models established with immunocompetent mice treated with an intratumoral injection of OAd-null, OAd-SIRPα-Fc, OAd-Siglec10-Fc, or OAd-TIGIT-Fc." (PMID 38016957, 2023). "Similar increases in CD8+ T cell infiltration in 4T1 or CT26 tumor tissues were observed after OAd-Siglec10-Fc or OAd-TIGIT-Fc treatments." (PMID 38016957, 2023). "CD24 is highly expressed on tumor cells and it binds to sialic acid-binding Ig like lectin 10 (Siglec10) to inhibit the clearance of tumor cells." (PMID 37834319, 2023). "A total of five potentially targetable tumor antigens were identified (PTPRC, SIGLEC10, CARD11, LILRB1, ADAMDEC1); high antigen expression was associated with prolonged OS and DFS, as well as higher tumor infiltration by antigen-presenting cells." (PMID 36992220, 2023). "This suggested that combination immunotherapy with anti-PD-1 and OAd-Siglec10-Fc significantly enhanced the suppression of tumor growth by activating multiple immune signaling pathways in the 4T1 tumor model." (PMID 38016957, 2023). "In fact, tumour‐expressed CD24 promoted immune evasion through its interaction with the inhibitory receptor sialic‐acid‐binding Ig‐like lectin 10 (Siglec‐10), expressed by M2‐like TAMs." (PMID 37654003, 2023). "Our results suggested that OAd-SIRPα-Fc and OAd-Siglec10-Fc both showed outstanding efficacy in tumor suppression of macrophage-dominated tumors, while OAd-TIGIT-Fc showed the best antitumor immunity in CD8+ T-cell-dominated tumors." (PMID 38016957, 2023). "CD24, a heavily glycosylated glycosylphosphatidylinositol‐anchored surface protein, interacts with Siglec‐10 to modulate the tumor immune response." (PMID 36866919, 2023). "Tumor growth suppression of both the treated and contralateral tumors by OAd-Siglec10-Fc was confirmed in 4T1 models." (PMID 38016957, 2023). "Immunoblot analysis showed that tumor cells infected with OAd-SIRPα-Fc, OAd-Siglec10-Fc or OAd-TIGIT-Fc efficiently secreted the corresponding fusion protein as a dimer into the supernatant in vitro." (PMID 38016957, 2023). "The engineered OAd-SIRPα-Fc and OAd-Siglec10-Fc generated in this study showed outstanding efficacy in tumor suppression in macrophage-dominated tumors." (PMID 38016957, 2023). "Genetic ablation of Siglec‐10 robustly resulted in a macrophage‐dependent reduction of tumor growth." (PMID 34914196, 2022). "Taken together, these findings indicate that Siglec‐10 was enriched in tumor‐infiltrating T cells and may represent a suppressed subpopulation or state in tumor immunity." (PMID 39373395, 2024).